OSBP (oxysterol binding protein)
Diseases named in the same sentence as OSBP in open-access papers:
OSBP is named in the same sentence as 33 diseases in open-access papers, as found by Europe PMC text mining. Sharing a sentence is not in itself a finding about the gene and the disease. The quoted sentences say what the papers report.
viral infection (4 papers, 2020 to 2024). "The interaction of VAP-A with OSBP also plays an important role in cholesterol homeostasis and viral infection." (PMID 39081319, 2024). "The concept of membrane contact sites (MCSs) in virus infection was established by the discovery of oxysterol-binding protein (OSBP) as the target of minor enviroxime-like compounds, and as the effector of PI4KB or of PI4KA in virus replication." (PMID 32322249, 2020). "In other circumstances, the substrate of OSBP can combat virus infection." (PMID 39039546, 2024). "Besides cholesterol, viral infection also regulates the localization of OSBP." (PMID 39081319, 2024). "Intracellular cholesterol homeostasis is essential for many viral infections, and mammalian VAP-A and OSBP have been shown to regulate intracellular cholesterol content." (PMID 39081319, 2024).
leukemia (3 papers, 2021 to 2025). A malignant (clonal) hematologic disorder, involving hematopoietic stem cells and characterized by the presence of primitive or atypical myeloid or lymphoid cells in the bone marrow and the blood. "Chemical, genetic and proteomic approaches were used to elucidate the mode of action of orpinolide, a withanolide-inspired OSBP inhibitor, revealing sterol transport as a druggable metabolic dependency in leukemia." (PMID 38907113, 2025). "Downregulation of AKT signaling can therefore be considered a downstream consequence of OSBP inhibition, hence rationalizing why leukemia cells, especially T cell-derived ALL, are more sensitive to orpinolide treatment." (PMID 38907113, 2025). "Importantly, we disentangle the cellular efficacy of orpinolide by showing that it predominantly emanates from targeting OSBP, reaffirming it as a putative therapeutic target in the context of leukemia." (PMID 38907113, 2025). "In an attempt to correlate the observed functional outcomes following OSBP inhibition with the antiproliferative effect of orpinolide in leukemia, we investigated whether OSBP overexpression could confer resistance to orpinolide." (PMID 38907113, 2025). "In line with our work, it has recently been described that T-ALL and leukemia stem cells highly express the oxysterol-binding protein (OSBP)-related protein 4 ORP4L, which acts as an adaptor/scaffold assembling CD3ε, Gαq/11, and PLCβ3 into a complex that activates PLCβ3." (PMID 33440859, 2021). "To validate these pooled screening results in an arrayed format in the context of leukemia, we conducted a CRISPR-based dropout experiment in KBM7 and Jurkat cells by inducing either single or dual OSBP/OSBP2 knockout(s)." (PMID 38907113, 2025). "We thus wanted to investigate if functional interference with OSBP, ORP4 or both recapitulates the orpinolide-induced vulnerability phenotype of leukemia cells." (PMID 38907113, 2025). "Importantly, we verify that OSBP is the predominant metabolic dependency in leukemia cells and that ORP4 is largely dispensable, and we reaffirm sterol transport at ER–Golgi MCSs as a potentially druggable vulnerability in leukemia cells." (PMID 38907113, 2025).
Salmonella Infections (2 papers, 2015 to 2025). Infections with bacteria of the genus SALMONELLA. "This interaction can lead to the exploitation of OSBP dependent pathways altered during the Salmonella infection." (PMID 26257716, 2015).
Alzheimer disease (1 paper, 2020). A progressive, neurodegenerative disease characterized by loss of function and death of nerve cells in several areas of the brain leading to loss of cognitive function such as memory and language. "Genes identified by our method suggest putative roles of several biological processes in Alzheimer’s disease, including mitochondrial dysfunction (indicated by UQCR11, MTCH2 and TMEM135), cholesterol transportation (indicated by TMEM135 and OSBP), and neuron activity (indicated by ADRA1A)." (PMID 33137096, 2020).
cardiovirus infection (1 paper, 2015). "We hypothesized that in cardiovirus infection, PI4P may serve to recruit OSBP and cholesterol to viral replication sites." (PMID 26406250, 2015).
cervical cancer (1 paper, 2022). A primary or metastatic malignant neoplasm involving the cervix. "In cervical cancer, it can induce mislocalization of Oxysterol-Binding Protein and trigger the apoptotic Golgi stress response." (PMID 36133816, 2022).
chondrosarcoma (1 paper, 2025). A malignant cartilaginous matrix-producing mesenchymal neoplasm arising from the bone and soft tissue. "To investigate whether OSBP inhibition affected the anterograde transport of cargo between the ER and the Golgi, we examined the trafficking of type 2 procollagen (PC2) in rat chondrosarcoma (RCS) cells." (PMID 38907113, 2025).
choroideremia (1 paper, 2023). Choroideremia (CHM) is an X-linked chorioretinal dystrophy characterized by progressive degeneration of the choroid, retinal pigment epithelium (RPE) and retina. "Physiological interactors of Rab 7 are RILP, OSBP and the Rab escort protein 1 or CHM choroideremia protein, which is the substrate-binding subunit of the Rab geranylgeranyltransferase complex." (PMID 37243184, 2023).
coinfection (1 paper, 2021). The simultaneous infection of a host by multiple pathogen species. "According to our data set, miR-122-5p is downregulated in HIV/HCV coinfection and modulates the expression of COPA and OSBP." (PMID 34829855, 2021).
colon cancer (1 paper, 2025). "In this study, we found OSW-1, a natural compound and OSBP inhibitor, potently and selectively kills colon cancer cells by activating a previously unknown necroptosis pathway that is independent of receptor-interacting protein 1 (RIP1) and RIP3." (PMID 40329104, 2025).
cyst (1 paper, 2024). A sac-like closed membranous structure that may be empty or contain fluid or amorphous material. "While only ∼35% of the cysts showed irregular morphology in the control siRNA-nucleofected cells, ∼50% of the OSBP-silenced cyst population showed luminal morphology defects." (PMID 37991810, 2024). "Remarkably, after 5 h of OSBP inhibition, conditions under which the cyst structure was still visible, significant drops in cholesterol levels in both apical and basolateral plasma membrane regions were observed." (PMID 37991810, 2024).
dyslipidemia (1 paper, 2019). "The pathogenic variants in the OSBP/ORP family members have been shown to cause diseases (such as dyslipidemia, cardiovascular disease)." (PMID 30894143, 2019).
enterovirus infection (1 paper, 2023). "OSBP is a regulator of lipid homeostasis and has been shown to exchange cholesterol with PI4P lipids in ROs and affect enterovirus infection." (PMID 37436162, 2023).
fungal infections (1 paper, 2021). "Posaconazole is an antifungal agent used in the prevention of invasive fungal infections and is also shown to inhibit the entry of Chikungunya virus and replication of Zika and Dengue viruses by binding to oxysterol-binding protein (sterol transporter)." (PMID 33841751, 2021).
hepatoma (1 paper, 2022). "Moreover, the knockout of ORP2, an oxysterol binding protein (OSBP)-related protein identified as a unique transporter of the labile chol pool from the ER to the PM, impairs hepatoma cell migration and adhesion through disorganization of F-actin and lamellipodia." (PMID 35819726, 2022).
liposarcoma (1 paper, 2025). A usually painless malignant tumor that arises from adipose tissue. "As OSBP is likely a tumour-promoting protein, repressing its expression by miR-195 can slow liposarcoma development." (PMID 39736850, 2025). "Subsequent molecular analyses identified oxysterol-binding protein (OSBP) as the direct target of miR-195 and increased miR-195 expression inhibited (p < 0.05) liposarcoma cell growth and migration in vitro and in vivo." (PMID 39736850, 2025).
lung adenocarcinoma (1 paper, 2024). A carcinoma that arises from the lung and is characterized by the presence of malignant glandular epithelial cells. "By analyzing lung adenocarcinoma (LUAD) survival data, we found that high OSBP and OSBPL2 expressions are associated with significantly longer patient survivals, suggesting that downregulation of these genes is a signature of tumor malignancy." (PMID 37991810, 2024).
pancreatic cancer (1 paper, 2025). "Dysregulation of OSBP has been demonstrated to influence the survival of breast cancer patients, and OSBP-related proteins such as ORP2 have been recorded to increase EMT activities in cancers like pancreatic cancer to accelerate cancer progression." (PMID 39736850, 2025).
poliovirus infection (1 paper, 2015). An disease or disorder caused by infection with Enterovirus C. "Oxysterol-binding protein (OSBP) has been demonstrated to be responsible for the transport of cholesterol and PI4P between the endoplasmic reticulum (ER) and Golgi, a pathway stimulated during poliovirus infection." (PMID 26473912, 2015).
psoriasis (1 paper, 2022). An autoimmune condition characterized by red, well-delineated plaques with silvery scales that are usually on the extensor surfaces and scalp. "If 7KC may bind to OSBP and be transported by OSBP, then OSBP might be a potential therapeutic target against both steatohepatitis and psoriasis." (PMID 36555497, 2022).
T-cell leukemia (1 paper, 2022). A malignant disease of the T-lymphocytes in the bone marrow, thymus, and/or blood. "Here, we report that oxysterol-binding protein (OSBP)-related protein 4 L (ORP4L) is expressed in adult T-cell leukemia (ATL) cells but not normal T-cells." (PMID 35906240, 2022).
infection (12 papers, 2012 to 2025). The state of being infected such as from the introduction of a foreign agent such as serum, vaccine, antigenic substance or organism. "In RD(ΔPI4KB) cells (i.e., PI4KB/OSBP-independent infection), the 3A-R54W mutation conferred a small or almost invisible plaque phenotype (mutant 1)." (PMID 34468191, 2021). "These mutations confer enhanced replication in PI4KB/OSBP-independent infection concomitantly with an increased ratio of viral plus-strand RNA to the minus-strand RNA." (PMID 34468191, 2021). "In this study, we analyze the roles of the 2B-Q20H and 2C-M187V mutations in PI4KB/OSBP-independent infection." (PMID 34468191, 2021). "This work reveals the essential roles of functional coupling and high-order, multitiered epistasis conferred by mutations in PI4KB/OSBP-independent infection." (PMID 34468191, 2021). "Collectively, these results suggested that the 2B-Q20H mutation, but not the 2C-M187V mutation, could confer enhanced infectivity, viral growth, and viral spread in PI4KB/OSBP-independent infection via recessive epistasis between the 3A-R54W/2B-F17L mutations." (PMID 34468191, 2021). "Therefore, we quantified the ratio of viral plus-strand RNA to the minus-strand RNA in PI4KB/OSBP-independent infection and analyzed the effects of the mutations on the ratio." (PMID 34468191, 2021). "During the infection by some viruses, OSBP is exploited to facilitate the trafficking of lipid components to promote viral replication." (PMID 39039546, 2024). "The potential antiviral effects on PI4KB/OSBP-independent replication was analyzed in the infection of the ΔPI4KB-resistant (−2C) mutant in RD(ΔPI4KB) cells." (PMID 37112883, 2023). "In this study, we found that viral spread from infected cells is the bottleneck of the PV 3A-R54W mutant in PI4KB/OSBP-independent infection." (PMID 34468191, 2021). "Strikingly, during infection of iPSDMs, endogenous OSBP re-localized to M. tuberculosis wt." (PMID 37676004, 2023). "Additionally, infection of OSBP-depleted, or VAPA/B double knockout cells resulted in increased cytoplasmic S. Typhimurium, suggesting a stabilization role of OSBP and VAPA/B for the SCV." (PMID 37223745, 2023). "These proteins are potential candidates for OSBP-mediated ER-dependent repair during infection." (PMID 37676004, 2023). "Delayed RO formation under PI4KB inhibition has been observed in infection of a CVB3 3A mutant, thus enhancement of the replication rate might serve as a specific determinant for evolution toward PI4KB/OSBP-independent infection." (PMID 34468191, 2021). "The ratio of viral plus-strand RNA to the minus-strand RNA in PI4KB/OSBP-independent infection." (PMID 34468191, 2021). "The 2B-F17L mutation enhanced the infectivity without enhancing the replication rate or level in PI4KB/OSBP-independent infection via recessive epistasis between the 3A-R54W mutation." (PMID 34468191, 2021). "The 3A and 2B mutations could confer specific enhancement of the replication level and rate in PI4KB/OSBP-independent infection concomitantly with an increased ratio of the RNAs." (PMID 34468191, 2021). "We further used OSW-1, an OSBP ligand that interferes with normal OSBP functioning, to pharmacologically inhibit OSBP and analyze whether its lipid transfer function is linked to EMCV infection." (PMID 26406250, 2015). "Adaptation of PV in PI4KB/OSBP-independent infection reached a plateau after five passages with four mutations fixed, suggesting that the roles of the PI4KB/OSBP pathway in the infection could be largely defined in three steps with the 3A-R54W/2B-F17L/2B-Q20H mutations." (PMID 34468191, 2021). "Recent work has proposed that SseL binds to oxysterol-binding protein (OSBP), and interferes with lipid metabolism, leading to the clearance of lipid droplets, which otherwise accumulate during infection of mice gallbladder epithelial cells." (PMID 22719249, 2012).
infection (continued). "The replication rate/level and infectivity were not fully restored (about 30% to 40% of those in PI4KB/OSBP-dependent infection), consistent with observation in experimental evolution of an RNA virus with double mutations." (PMID 34468191, 2021). "Since PI4P lipids serve to accumulate OSBP and cholesterol at EMCV wt ROs, we next addressed the issue of whether OSBP and cholesterol were present at the ROs of EMCV 3A mutants when PI4KA was inhibited throughout infection." (PMID 27303747, 2016). "Cholesterol was redistributed to EMCV ROs upon infection, and treatment with AL-9 or OSW-1 resulted in a significantly reduced colocalization of cholesterol with 3AB, arguing that accumulation of cholesterol at ROs is mediated by both PI4KA and OSBP." (PMID 26406250, 2015). "Oxysterol-binding protein (OSBP), an important mediator the cellular lipid homeostasis and signal transduction, contributes to ROs development and unesterified cholesterol accumulation upon EVA71 infection, which enhances 3AB cleavage and viral plus-strand RNA synthesis." (PMID 40869312, 2025).
cancer (9 papers, 2015 to 2025). A tumor composed of atypical neoplastic, often pleomorphic cells that invade other tissues. "It is reported that the OSBP/ORPs family is implicated in cell proliferation and cancer development." (PMID 34631585, 2021). "Although OSW-1 exerts potent and selective anticancer effects, the question of how inhibition of OSBP by OSW-1 leads to cell death specific to cancer cells has remained unresolved for a long time." (PMID 39675715, 2025). "Dysregulation of the ORP family including OSBP and ORP4 has been implicated in cancer." (PMID 40329104, 2025). "Intriguingly, despite this, a comparison between the sensitivities of various cancer cell lines to orpinolide and the mRNA expression levels of OSBP or ORP4-encoding OSBP2 did not reveal significant correlations." (PMID 38907113, 2025). "In agreement with the cell-line collection data, OSBP and OSBPL2 expressions positively correlate with the epithelial features of the given cancer tissue specimens." (PMID 37991810, 2024). "Therefore, OSBP/ORPs may be potential therapeutic targets in cancer." (PMID 34631585, 2021). "A great number of studies have demonstrated that some OSBP/ORP members participate in cancer progression, but how OSBP/ORP family members influence cancer cell initiation and progression and the mechanism behind these processes remain unclear." (PMID 35127474, 2021). "Moreover, a series of natural products termed ORPphilins exert their antiproliferative effects on cancer cells by targeting ORP4L and its close relative OSBP." (PMID 27588468, 2016). "Furthermore, Shair and co-workers have shown that 1 also selectively binds to oxysterol binding protein (OSBP) and OSBP-related protein 4L (ORP4L) and drew attention to these proteins, whose role in cancer cell survival was little known at the time." (PMID 26473891, 2015). "Recently, some studies show that OSBP does not have any known role in cellular proliferation; while ORP4 participate in the control of human malignant tumor cell proliferation and survival." (PMID 34631585, 2021).
tumor (3 papers, 2019 to 2024). "ORP inhibitors (named ORPphilins), acting as antiproliferative agents, are crucial for the inhibition of tumor growth and are capable of attenuating OSBP or ORP4L." (PMID 35127474, 2021). "Oxysterol-binding protein (OSBP)-related protein 5/8 (ORP5/8) were the only two lipid transfer proteins anchored to ER membranes 27, 28 and ORP8 expression was closely related to tumor cell apoptosis 29-31." (PMID 31410188, 2019).
OSBP also shares sentences with these, for which no sentence is quoted: cardiovascular disease (1 paper); COVID-19 (1); deafness (1); glioblastoma (1); hearing loss (1); malaria (1); neurological disorders (1); Niemann-Pick disease (1); tuberculosis (1).